RNF11 (ring finger protein 11)
Description:
Essential component of a ubiquitin-editing protein complex, comprising also TNFAIP3, ITCH and TAX1BP1, that ensures the transient nature of inflammatory signaling pathways. Promotes the association of TNFAIP3 to RIPK1 after TNF stimulation. TNFAIP3 deubiquitinates 'Lys-63' polyubiquitin chains on RIPK1 and catalyzes the formation of 'Lys-48'-polyubiquitin chains. This leads to RIPK1 proteasomal degradation and consequently termination of the TNF- or LPS-mediated activation of NF-kappa-B. Recruits STAMBP to the E3 ubiquitin-ligase SMURF2 for ubiquitination, leading to its degradation by the 26S proteasome.
Synonyms: CGI-123; Sid1669p; MGC51169; SID1669
Tractability: PROTAC: UniProt records ubiquitination sites on it; its protein half-life has been measured.
Gene: Protein-coding gene on chromosome 1 (51,235,625 to 51,273,447, forward strand). Ensembl gene ENSG00000123091.
Subcellular location: Early endosome; Recycling endosome; Cytoplasm; Nucleus
Gene Ontology:
Molecular function: protein binding; ubiquitin protein ligase activity; DNA binding; zinc ion binding
Biological process: protein autoubiquitination; ubiquitin-dependent protein catabolic process
Cellular component: extracellular exosome; ubiquitin ligase complex; cytoplasm; early endosome; nucleus; recycling endosome
Genetic constraint (gnomAD): Loss-of-function variants: 3 observed, 14.43 expected, observed/expected ratio (o/e) 0.21, 90% interval 0.094 to 0.54. The upper end of that interval is the gene's LOEUF score, 0.54, which puts it in group 2 of 6, group 1 being the genes least tolerant of losing a copy. Missense variants: 132 observed, 195.57 expected, observed/expected ratio (o/e) 0.67, 90% interval 0.58 to 0.78. Synonymous variants: 65 observed, 73.69 expected, observed/expected ratio (o/e) 0.88, 90% interval 0.72 to 1.08.
Homologues: Orthologues: chimpanzee RNF11 (100% identical), dog RNF11 (100% identical), guinea pig RNF11 (100% identical), pig RNF11 (100% identical), rabbit RNF11 (100% identical), mouse Rnf11 (99% identical), rat Rnf11l2 (99% identical), tropical clawed frog rnf11 (95% identical), zebrafish rnf11b (94% identical), Caenorhabditis elegans C01G6.4 (38% identical). Paralogues in human: ZNRF1 (30% identical), ZNRF2 (27% identical).